SPP1 (secreted phosphoprotein 1)
Diseases named in the same sentence as SPP1 in open-access papers (continued):
Sharing a sentence is not in itself a finding about the gene and the disease.
cancer (continued). "As expected, both SPP1 and CYP24A1 were more induced in CSCs compared to their corresponding bulk cancer cells by the same dose of calcitriol, indicating that CSCs are more sensitive to low dose calcitriol in the activation of the VDR pathway signaling." (PMID 29581858, 2018). "We then treated 2008 and Kuramochi CSCs and their corresponding bulk cancer cells with calcitriol, and analyzed expression of two VDR downstream genes SPP1 and CYP24A1, which possess vitamin D-responsive element." (PMID 29581858, 2018). "Osteopontin (OPN; secreted phosphoprotein 1 or SPP1) is a glycoprotein secreted by a number of types of cells including inflammatory, immune, fibroblast, osteoblast, and cancer cells." (PMID 28595626, 2017). "These genes belong to relevant intracellular signaling pathways in cancer such as PI3K-Akt (COL4A2, MYC, PDGFA, SPP1), proteoglycans (HIF1A, MYC, PLAUR, TGFB1), and Hippo (CTGF, MYC, NF2, TGFB1)." (PMID 29075357, 2017). "Among the genes that appeared down-regulated by CBX7 expression we focused on the SPP1, SPINK1 and STEAP1 genes since their expression has been found overexpressed in human carcinomas." (PMID 24865347, 2014). "Gene expression profiling analysis identified SPP1, CTHRC1and GREM1 as potential biomarkers for early diagnosis of the cancer, and SPINK1 and BMP7 to distinguish between AC and SCC in small biopsies or in blood samples." (PMID 24299561, 2013). "Thus, SPP1 may be a promising common target of cancer therapy and prevention." (PMID 17989776, 2007). "Moreover, pan-cancer analysis also demonstrated a high correlation between VSIG4 and SPP1 in myeloid cells." (PMID 39920772, 2025). "We discovered 22 hub genes influencing patient survival, among which COL3A1, PLAU, and SPP1 stood out for their overexpression in cancer compared to normal tissues." (PMID 41465316, 2025). "Similar to Spp1, Calr expression was the most prominent in late‐stage 4T1 cancer cells, although the difference was not statistically significant." (PMID 39939411, 2025). "A study has indicated that macrophage polarity, defined by the expression of CXCL9 and SPP1 rather than traditional M1 and M2 markers, controls human cancers." (PMID 40416872, 2025). "With an IV injection, this counteracted SPP1‐TAM and thus promoted cancer cures." (PMID 39639496, 2025). "The discovery of SPP1+ macrophages in both cancer and noncancer conditions raises fundamental questions about the current classification of macrophages." (PMID 40047497, 2025). "Additionally, we found that the level of secreted phosphoprotein 1 (SPP1), which is involved in the progression of many cancers, was dramatically decreased in USP24C1695A mice." (PMID 40448065, 2025). "Finally, we calculated the prevalence for SPP1 and C1QC high versus low TAM bins within each cancer indication." (PMID 41415295, 2025). "In aggressive cancers (e.g., pancreatic and thyroid cancer), lactate-induced histone H3 lysine 18 lactylation (H3K18la), mediated by VSIG4+ TAMs activates STAT3, which binds to the SPP1 promoter and enhances its transcription." (PMID 41425545, 2025). "At present, there are no specific drugs targeting SPP1 for cancer treatment, highlighting an unmet need." (PMID 41391064, 2025). "Additionally, stClinic predicts a niche promoting CRC cells adaptive to normal liver tissue, featuring SPP1+ MTRNR2L12+ myeloid cells and CAFs by integrating primary and metastasis cancers." (PMID 40523901, 2025). "Furthermore, SPP1 increases the expression of MMPs, particularly MMP-2 and MMP-9, which degrade the ECM and create a favorable environment for cancer cell invasion and metastasis." (PMID 40559389, 2025). "Furthermore, MHC-II+ cancer cells spatially colocalized with CD8+ T cells, regulatory T cells, and SPP1+ macrophages, where they engaged with inhibitory receptors on these immune cells, promoted CD8+ T cell exhaustion and facilitated immune evasion." (PMID 41281745, 2025).
cancer (continued). "Extensive independent studies have demonstrated that SPP1, as an oncogene, promotes the progression of these malignancies, particularly through its role in mediating pathological remodeling of the ECM across these cancer types." (PMID 41293726, 2025). "This creates a feedback loop where SPP1 activates the SPP1/CD44 axis and downstream PI3K/AKT and MAPK pathways, promoting epithelial-mesenchymal transition (EMT), autophagy, aberrant glucose metabolism, and reduced drug uptake in cancer cells." (PMID 41391064, 2025). "We were the first study to link SPP1 and EMT process with LINC01133 over-expression, demonstrating a novel SPP1 regulation network that may be beneficial in future anti-cancer therapy." (PMID 38987572, 2024). "Finally, we performed KEGG enrichment analysis of SPP1 signaling pathway receptors (CD44, ITGB1, ITGB6) that were expressed in epithelial cells in 33 cancers, and extracted the intersections of the enriched pathways." (PMID 38648200, 2024). "Meanwhile, we emphasized the role of secretory SPP1 on the PMN rather than the cancer cell itself in this study." (PMID 39529085, 2024). "This hypothesis is supported by previous studies on multiple cancers, which have proposed therapies that target SPP1 or disrupt the interaction between SPP1+TAM and other cells as potential treatment for multiple types of cancer." (PMID 38515213, 2024). "The results indicated a negative correlation between SPP1 and various cellular processes, including cell metastasis, epithelial-mesenchymal transition, angiogenesis, DNA damage, cell quiescence, cancer cell invasion, and cell differentiation." (PMID 38329443, 2024). "Secreted SPP1 may bind to CD44 and integrins altering cell signalling pathways favouring cancer progression." (PMID 38535967, 2024). "The cancer cells in CCC predominately secreted ligands for pathways such as MIF and SPP1." (PMID 39149248, 2024). "To decipher the relationship between TAM polarization and cancer stemness, we stratified the TAMs into M2high (LGMN+ and SPP1+ TAMs) and M2low (the remaining TAMs) based on M2 signature scores and subsequently analyzed the cell-cell communication pinpointing ligand-receptor interactions." (PMID 38169544, 2024). "Additionally, cancer-related pathways such as hypoxia, EMT, glycolysis, and angiogenesis were strongly enriched in SPP1+ TAMs." (PMID 37853464, 2023). "Interestingly, we also observed that the expression of CDH2, SPP1, TNC, CYR61, SERPINA1, and IL6 correlated with the progression of individual cancer stages." (PMID 37887075, 2023). "Our research has emphasized the correlation between high SPP1 counts and well-known negative histological prognostic factors in cancer, including tissue necrosis and inflammation." (PMID 38275392, 2023). "Our regression modeling of cancer mRNA expression data from over 11,000 patients in the TCGA PANCAN database suggested that heme exposure, measured by HMOX1 expression, strongly predicts SPP1." (PMID 38060331, 2023). "The clearest consequence of exposing macrophages to carcinoma cells culture (with or without CAFs) was polarization toward an SPP1+ state." (PMID 38036590, 2023). "Although the production of SPP1 by TAMs has been attracting much attention recently, there have been no studies distinguishing the SPP1 expression of cancer cells and TAMs." (PMID 36139536, 2022). "One pan-cancer study showed that SPP1+ TAMs with the M2 phenotype were found in several cancers but not in GC." (PMID 36612160, 2022). "Since cancer cell proliferation was not influenced by SPP1 and macrophage-derived factors in a two-dimensional (2D) culture system (unpublished data), we focused on the chemoresistance of cancer cells." (PMID 36139536, 2022). "In contrast, in SCC, the scores for SPP1 on cancer cells and TAMs were not correlated with the prognosis." (PMID 36139536, 2022). "The CM of macrophages, but not SPP1, significantly promoted cancer cell growth with or without the anti-cancer drugs." (PMID 36139536, 2022).
cancer (continued). "Moreover, Spp1–Cd44 interactions were also enriched in the CEER, thus forming a cancer-promoting crosstalk that resulted in the invasiveness of epithelial cells." (PMID 36612160, 2022). "In adenocarcinoma, the scores for SPP1 on cancer cells were not correlated with the prognosis, whereas high scores for SPP1 on TAMs were found to predict a poor prognosis." (PMID 36139536, 2022). "Secreted phosphoprotein 1 (SPP1) is overexpressed during the development and progression of different cancers and might act as a potential prognostic biomarker and therapeutic target." (PMID 33568167, 2021). "Conceivably, the cancer EMT and glycolysis program promoted by SPP1+ TAMs may also be accelerated by hypoxia TME, as there is a strong correlation between the abundance of SPP1+ TAMs and EMT, glycolysis, and hypoxia." (PMID 34676217, 2021). "Thus, we reasoned that SPP1 was upregulated, and SPP1+ TAMs were expanded in hypoxia TME, interacting with cancer cells to promote malignant biological characteristics and thus bring poor survival of patients." (PMID 34676217, 2021). "We distinguished that SPP1+ TAMs, expanded under hypoxia TME, might promote the EMT and glycolysis program of cancer cells and might be related to worse survival in multiple cancer types." (PMID 34676217, 2021). "SPP1 and CXCL12 are chemokines demonstrated to stimulate angiogenesis both during normal organ development and under pathological conditions, such as various cancers." (PMID 34099632, 2021). "In our results, TMPO-AS1/miR-126-5p/SPP1 and CARD8-AS1/miR-21-5p/TEK are not only related to LUAD progression, but also function as immunotherapeutic targets for LUAD, clarifying a novel mechanism in cancer therapy." (PMID 34149807, 2021). "Next, we pooled all the 20 cancer types and found that all the three markers were prognosticator of solid cancers (SPARC: HR = 1.10, 95% CI = [1.01, 1.20], p = 0.028; SPP1: HR = 1.25, 95% CI = [1.14, 1.36], p < 0.001; BGLAP: HR = 1.13, 95% CI = [1.04, 1.24], p = 0.005)." (PMID 33240930, 2020). "Besides, Secreted phosphoprotein 1 (SPP1), an integrin-binding participating in tumorigenesis and metastasis, is over-expressed in numerous cancers, including HCC." (PMID 32951492, 2020). "However, there are some cancers such as LIHC, READ, and PAAD showed better prognosis when SPP1 was highly expressed." (PMID 33324676, 2020). "Particularly, SPARC and SPP1 expression were positively correlated to DC-related markers CD86, NRP1, and inhibitory checkpoint markers including LAIR1, HAVCR2, and PDCDLG2 in most cancer types." (PMID 33240930, 2020). "Importantly, the bone sialoprotein (IBSP) and osteopontin (SPP1) coding genes, which are regulated by RUNX2, play important roles in bone metastases derived from osteotropic cancers." (PMID 32204402, 2020). "To resolve these inconsistencies, we systematically analyzed the available data to determine whether SPP1 and SPP2 are prognostic markers in the context of human cancer." (PMID 31849319, 2019). "We therefore defined the species-conserved healing wound cytokines (HWCs) as SPP1, IL1B and IL6, and considered whether the expression levels of these genes might have prognostic value in human cancers." (PMID 30054470, 2018). "Future studies may reveal whether the same mechanism also applies when SPP1 and TNC are produced by the cancer stroma." (PMID 30190333, 2018). "Interestingly, cerivastatin but not pravastatin treatment of PA-TU-8902 cells significantly decreased the expression of SPP1 and SOX2, factors with important role in cancer metastasis and aggressiveness." (PMID 27175805, 2016). "This is especially in view of the fact that no copy number alterations involving SPP1 have previously been reported in a variety of cancers and tissue types (by reference to COSMIC and CONAN), including NF1 MPNSTs." (PMID 25884485, 2015).
cancer (continued). "For example, the “Cancer, Cellular Movement, Cellular Growth and Proliferation” network encompasses EGFR, FGFR2 and other key genes, such as AURKA, a cell cycle checkpoint mediator, and SPP1, LAMA3 and GJA1, which play a role in cell communication." (PMID 23383013, 2013). "Claudin 1 knockdown also resulted in a significant up regulation of the expression of EMT related genes, SERPINE 1 (plasminogen activator inhibitor type 1, PAI1) and secreted phosphoprotein 1 (SSP1; also known as osteopontin) that have been shown to suppress cancer cell migration." (PMID 23721519, 2013). "SPP1, CTHRC1 and GREM1 are candidate biomarkers to identify the cancer." (PMID 24299561, 2013). "Transforming growth factor gene (Tgfbi), Spp1 and ITGA5 were up regulated in cancer cells." (PMID 22321936, 2012). "Likewise, senescence‐positive cancer cells tended to interact with T cells or VasECs via the SPP1 pathway more intensively than senescence‐negative counterparts." (PMID 39231761, 2025). "Furthermore, the results showed an additive phenotype between Spp1 and NET formation, in which Spp1high NEThigh cancers have significantly increased epithelial-to-mesenchymal transition (EMT) scores, suggesting that OPN promotes invasion through NETs in the metastatic cascade." (PMID 40865052, 2025). "Overall, the strong and stable binding between SPP1 and CD44 suggests that future therapeutic strategies could involve small molecules designed to block their interaction, potentially enhancing the efficacy of cancer immunotherapy." (PMID 41425595, 2025). "Taken together, our results demonstrate VSIG4-H3K18la-SPP1 signaling, beyond the checkpoint function of VSIG4 directly inhibiting T cells, confers on TAMs an emerging way to foster the immunosuppressive microenvironment and impair antigen-specific immunity against aggressive cancers." (PMID 39920772, 2025). "The results indicated that regions with high HIF1A expression were correlated with an increased accumulation of SPP1+CD68+TAMs and HIF1A+ɑSMA+CAFs, suggesting the role of hypoxia in promoting the formation of the aggressive multicellular community and thus accelerating cancer progression in TNBC." (PMID 40432877, 2025). "However, in B16F10/shDRG2 tumors, anti-PD-1 treatment did not decrease the percentage of cancer cells in subcluster “Spp1 + ” but increased it." (PMID 38802348, 2024). "Meanwhile, cancer metastasis is a muti-steps and complex process, SPP1 could increase the opportunity of metastasis rather than necessarily lead to HCC lung metastasis." (PMID 39529085, 2024). "In-vivo studies have highlighted how SPP1− knockout mice have been shown to lead to decreased M0/M2 infiltration, a decrease in fibrosis, and exhibit positive results in OS59,60; despite these encouraging results, no current human clinical studies inhibiting SPP1 have been conducted on cancer." (PMID 39075108, 2024). "Furthermore, a recent study redefines macrophage polarity on the basis of their expression of CXCL9 and SPP1, as opposed to traditional “M1” and “M2” markers, with this signature displaying prognostic significance across multiple cancer types." (PMID 39165364, 2024). "To validate the differential distribution of myeloid cell subtypes in other cancer types, we classified subtypes of myeloid cells according to the clustering of sub-spot GEPs in HCC tissues, including monocytes, TGFB1+ macrophages (Macro-TGFB1), Macro-SPP1, and MACRO+ macrophages (Macro-MARCO)." (PMID 36806082, 2023). "Finally, we evaluated the expression of hub genes with the development of one of the main complications of IPF patients, LUAD and LUSC, and observed that six of them (CDH2, SPP1, TNC, CYR61, SERPINA1, and IL6) were correlated with the progression of different cancer stages." (PMID 37887075, 2023).
cancer (continued). "We also determined that TREM2+ TAMs highly expressed soluble factors such as SPP1, APOE, C1QA, C1QB, and C1QC, which suggested that this TREM2+ TAMs subset may be exocrine or paracrine for establishing the microflora critical for cancer cell invasion and the metastasis environment." (PMID 37187751, 2023). "Moreover, SPP1 expression was significantly related with the levels of infiltrating CD8 + cells, CD4 + cells, macrophages, neutrophils and dendritic cells in different types of cancers." (PMID 36585688, 2022). "In contrast, the scores for SPP1 on cancer cells were not correlated with any factor." (PMID 36139536, 2022). "SPP1 also modulates the TME by functioning as a chemotaxis factor for various immune cells, including neutrophils, macrophages, and dendritic cells; however, to the best of our knowledge a role for SPP1 as a NET stimulator in cancer has not yet been identified." (PMID 35432310, 2022). "Besides VEGFA which was widely known and applied in anti-angiogenic therapy, in our pan-cancer analysis, some genes, like SPP1, STC1 and COL5A2, were not only highly expressed in most tumors, but also risk factors of prognosis." (PMID 36479101, 2022). "The results indicate that SPP1+ TAMs may interact with cancer cells in a paracrine pattern through expressing and secreting SPP1 then binding to cell-surface receptor CD44, consistent with a previous work, showing that CD44 is the receptor of SPP1 to regulate cancer metastasis." (PMID 34676217, 2021). "It was reported that SPP1 could regulate MMP-2 and MMP-9 expression and promote extracellular matrix degradation via activating αvβ-NF-κB pathway, and thus accelerate the growth, migration and invasion of cancer cells." (PMID 33240930, 2020). "Our findings indicate that SPP1 and SPP2 genes might play an important role in cancer progression." (PMID 31849319, 2019). "Notably, SPP-1 upregulation is inducible by PKC activation, a signaling pathway triggered by TAAR1 agonists, and its expression is inversely related to cancer prognosis as tumors rich in the SPP-1 gene have an enhanced ability to grow and invade other tissues to ultimately metastasize." (PMID 29997511, 2018). "We find that JNK signaling, that is active in a subpopulation of cancer cells within tumors, induces a stem cell and wound healing gene expression program that includes a number of extracellular matrix (ECM) proteins such as osteopontin (SPP1) and tenascin C (TNC)." (PMID 30190333, 2018). "Through functional analysis, we found that SPP1+ TAMs did not perform common antigen-presenting functions but are involved in the extracellular matrix (ECM) remodeling, which makes us suspect their functional promotion with cancer-associated fibroblasts (CAFs)." (PMID 40230843, 2025). "This phenomenon may have important implications in cancer, as enteric glial cells are particularly abundant in CRC, and healthy enteric glial cells have been shown to induce a macrophage phenotype distinct from the SPP1+ subset, further highlighting the pro‐tumorigenic role of SPP1+ TAMs." (PMID 40395129, 2025). "Genes upregulated by >1.5‐fold in cancer tissues rather than in normal intestinal mucosae include Wnt signaling‐related genes such as Fzd1 (fold change [FC], 5.6), Myc (FC, 2.6), Ccnd1 (FC, 1.6), Mmp2 (FC, 10.4), Mmp7 (FC, 16.0), Mmp8 (FC, 12.9), Mmp12 (FC, 52.2), and Spp1 (FC, 149.3)." (PMID 35274815, 2022). "However, in previous studies, SPARC/SPP1/BGLAP was deemed independent functional molecule rather than marker of osteomimicry, and was investigated separately in different cancer types and no one had combined these molecules and explored their prognostic value in pan-cancer analyses." (PMID 33240930, 2020). "We found that BaP or CXCL13 treatment or SPP1 overexpression in lung epithelial or cancer cells did not up-regulate RANKL or Src (data not shown), but did activate β–catenin, suggesting that CXCL13 may induce an EMT via different mechanisms in different settings." (PMID 26565418, 2015).